UBA3 (ubiquitin like modifier activating enzyme 3)
Diseases named in the same sentence as UBA3 in open-access papers:
UBA3 is named in the same sentence as 33 diseases in open-access papers, as found by Europe PMC text mining. Sharing a sentence is not in itself a finding about the gene and the disease. The quoted sentences say what the papers report.
breast cancer (6 papers, 2020 to 2024). A primary or metastatic malignant neoplasm involving the breast. "After screening, source genes closely associated with canine mammary tumours were found to include RYR2, PDE4D, ROCK2, CREB3L2 and UBA3, and associated circRNAs included chr27:26618544-26687235-, chr26:8194880-8201833+ and chr17:7960861-7967766-." (PMID 35622733, 2022). "The Human Protein Atlas database, the Cancer Genome Atlas and Gene Expression Omnibus datasets were used to validate the expression levels of UBA3 in breast cancer." (PMID 33996822, 2021). "In the present report, we found that high glucose increased UBA3 mRNA levels by inhibiting UBA3 promoter methylation in breast cancer cells." (PMID 33996822, 2021). "Moreover, UBA3 expression is influenced by glucose level and epigenetic modifications, and UBA3 mediates the neddylation ofPTEN, a tumor suppressor gene, in breast cancer." (PMID 38298057, 2024). "Conversely, promoter methylation of UBA3 is downregulated in breast cancer." (PMID 33996822, 2021). "Then we performed a methylation-specific PCR assay to clarify whether glucose regulates the UBA3 promoter methylation in breast cancer cells." (PMID 33996822, 2021). "Low glucose reduced the mRNA level of UBA3 in breast cancer cells." (PMID 33996822, 2021). "Moreover, the mRNA level of UBA3 is negatively correlated with UBA3 promoter methylation level in breast cancer patients." (PMID 33996822, 2021). "Among breast cancer patients harboring high PTEN expression, the PI3K/Akt signaling pathway activation gene-set was markedly enriched in the genes encoding for the NEDD8-activating enzyme UBA3, whose expression was increased, and the deneddylase NEDP1, whose expression was decreased." (PMID 33996822, 2021). "In addition, we suggest that low levels of UBA3 promoter methylation in breast cancer patients could suggest promising tumor therapeutic targets." (PMID 33996822, 2021). "We also found that neither the SPOP-ASCT2 axis, nor NEDD8 and few neddylation enzymes, including E1 heterodimer NAE1/APPBP1, and UBA3/NAEβ, and two E2s, UBE2M and UBE2F is subjected to regulation by glucose deprivation in breast cancer cells." (PMID 35641493, 2022). "Recently, we reported that high glucose triggers UBA3 upregulation and downstream PTEN neddylation in breast cancer." (PMID 33996822, 2021). "We also demonstrate that high glucose conditions upregulate UBA3 mRNA by inhibiting UBA3 promoter methylation, and this upregulation results in the overactivation of PTEN neddylation in breast cancer cells." (PMID 33996822, 2021). "Western blot analysis showed that the expression levels of both NAE enzymes were significantly higher in the breast cancer cells, with the highest expression of APP-BP1 and UBA3 observed in the estrogen receptor alpha (ERα) positive MCF7 cells." (PMID 32839427, 2020). "Furthermore, we found that high glucose inhibits UBA3 promoter methylation and increases UBA3 mRNA levels, and these outcomes correlate with the overactivation of PTEN neddylation in breast cancer cells." (PMID 33996822, 2021). "UBA3 also modulates oxidative phosphorylation and the tricarboxylic acid cycle in breast cancer cells by affecting the neddylation of mitochondrial proteins, and the activity of the PI3K/AKT signaling pathway is positively correlated with the expression of UBA3." (PMID 38298057, 2024). "The PI3K/Akt signaling pathway is positively correlated with the expression of UBA3, but the correlation is not significant in PTEN-null breast cancer patients." (PMID 33996822, 2021).
glioblastoma (3 papers, 2017 to 2022). The most malignant astrocytic tumor (WHO grade IV). "NAE1 and UBA3 levels increased in glioblastoma patients; high NEDD8 levels were associated with poor clinical outcomes." (PMID 31771104, 2019). "Comparing the gene expressions associated with the neddylation pathway in public data including TCGA and Rembrandt, expression levels of the neddylation enzymes NAE1 and UBA3 were higher in glioblastoma than in the normal." (PMID 31771104, 2019). "Several recent studies have observed a correlation between overactivation of NEDD8 pathway components, including NEDD8, UBA3, NAE1, and Ubc12, with cancer progression and poor prognosis in human lung cancers, colorectal cancers, and glioblastomas." (PMID 28475037, 2017).
intrahepatic cholangiocarcinoma (2 papers, 2022 to 2024). A carcinoma that arises from the intrahepatic bile duct epithelium in any site of the intrahepatic biliary tree. "Another study shows that UBA3 promotes the occurrence and development of intrahepatic cholangiocarcinoma through the MAPK signaling pathway." (PMID 39202384, 2024).
leukemia (2 papers, 2014). A malignant (clonal) hematologic disorder, involving hematopoietic stem cells and characterized by the presence of primitive or atypical myeloid or lymphoid cells in the bone marrow and the blood. "Our results suggest that mutations in the UBA3 gene are a common mechanism for malignant leukemia cells to acquire resistance to MLN4924 in vitro." (PMID 24691136, 2014). "In this report, we describe two previously unreported and uncharacterized novel mutations in the UBA3 gene in two leukemia cell lines with acquired resistance to MLN4924." (PMID 24691136, 2014). "Similarly, treatment-induced mutations of NAEβ/UBA3 were reported to lead to secondary resistance to MLN4924 in leukemia, further mandating the development of combinational regiments including MLN4924 or novel next-generation NAE inhibitors." (PMID 25229838, 2014). "Nevertheless, these findings suggest that mutations located in different positions around the NEDD8 binding site of UBA3 cause changes in the catalytic pocket of the enzyme to reduce MLN4924 potency while allowing sufficient NEDD8 system function for leukemia cell survival." (PMID 24691136, 2014). "In summary, we have identified two mutations in UBA3 which were not previously reported or characterized and demonstrated that these mutations confer MLN4924 resistance in leukemia cell lines but do not impair normal function of the NAE enzyme and activity of the neddylation pathway." (PMID 24691136, 2014).
lung adenocarcinoma (2 papers, 2022 to 2023). A carcinoma that arises from the lung and is characterized by the presence of malignant glandular epithelial cells. "In this study, we investigated the relationships between the UBA3-dependent neddylation pathway and the infiltration of several immunosuppressive cell populations in lung adenocarcinoma (LUAD)." (PMID 37656220, 2023).
lung carcinoma (2 papers, 2017 to 2023). "The entire neddylation pathway is highly activated, and UBA3 expression level is higher in lung cancer than in adjacent normal tissues and is associated with poor overall patient survival." (PMID 37656220, 2023). "Therefore, we speculate that UBA3 may affect the behaviors of lung cancer cells and contribute to cancer-associated inflammation by regulating the NF-кB pathway." (PMID 37656220, 2023). "MLN4924, also known as pevonedistat, is a potent and highly selective small molecular inhibitor of UBA3, exhibiting effective antitumor activity in various types of cancer, including lung cancer." (PMID 37656220, 2023). "Furthermore, UBA3 and other neddylation enzymes are overexpressed in lung cancer tissues compared to adjacent normal tissues." (PMID 37656220, 2023). "UBA3 may be a major immune checkpoint and serve as a potential target for immunotherapy in lung cancer." (PMID 37656220, 2023). "To explore the regulatory mechanism of UBA3 in LUAD, we analyzed the mRNA expression profiles in A549 lung cancer cells from the solvent-treated and MLN4924-treated groups using mRNA sequencing (mRNA-seq) and conducted enrichment analyses." (PMID 37656220, 2023). "In summary, this study provides evidence that high levels of expression of UBA3 in LUAD may promote the infiltration of Th2 cells, Tregs, pDCs, and TAMs by promoting various tumor-derived factors, thus facilitating the progression of lung cancer." (PMID 37656220, 2023).
malaria (2 papers, 2018 to 2023). Malaria is a serious and sometimes fatal disease caused by a parasite that commonly infects a certain type of mosquito which feeds on humans. "Pevonedistat had comparable effects in a malaria murine model, where deficiency of UBA3, which encodes the catalytic subunit of the NAE, significantly compromised survival, activation, and proliferation of CD4+ T cells and impaired TH1/TFH differentiation." (PMID 37031300, 2023). "Therefore, TCR stimuli could induce Uba3 up-regulation and NEDD8 modification of target proteins, and that P. yoelii 17XNL-driven neddylation might allude to a potential role for this pathway in T cell-mediated defense against blood-stage malaria." (PMID 30462731, 2018).
melanoma (2 papers, 2014 to 2023). A malignant, usually aggressive tumor composed of atypical, neoplastic melanocytes. "It has been hypothesized that interfering with the expression of UBA3 may inhibit NEDD8 conjugation and, subsequently, prevent the proliferation of melanoma." (PMID 24765193, 2014).
Anxiety (1 paper, 2026). Intense feelings of nervousness, tension, or panic often arise in response to interpersonal stresses. "Inducible Uba3 deletion in microglia mitigates psychological stress-induced anxiety-like behavior." (PMID 41514502, 2026).
colitis (1 paper, 2026). Inflammation of the colon. "Myeloid deficiency of UBA3, the catalytic subunit of the NEDD8-activating enzyme (NAE), renders mice resistant to dextran sodium sulfate-induced colitis." (PMID 41514502, 2026).
glioma (1 paper, 2022). A benign or malignant brain and spinal cord tumor that arises from glial cells (astrocytes, oligodendrocytes, ependymal cells). "In the order of significance, high gene expression of UBA1, UBA6, and UBA3/NAE2 were associated with significantly shorter survival times in the French glioma dataset (chi = 26.79, p = 2.3 × 10−7, chi = 21.04, p = 4.5 × 10−6, chi = 8.79, p = 3.0 × 10−3, respectively)." (PMID 36293188, 2022).
Hyperglycemia (1 paper, 2024). An increased concentration of glucose in the blood. "Additionally, the hyperglycemia of flies expressing CUL1 in the whole body and HSD flies were rescued by UBA3, UBE2M, or RBX1 knockdown." (PMID 38212312, 2024).
kidney chromophobe (1 paper, 2023). "Conversely, the level of expression of UBA3 was down-regulated compared to adjacent normal controls in malignancies such as kidney chromophobe (KICH), kidney renal clear cell carcinoma (KIRC), and thyroid carcinoma (THCA)." (PMID 37656220, 2023).
non-small cell lung carcinoma (1 paper, 2020). A group of at least three distinct histological types of lung cancer, including non-small cell squamous cell carcinoma, adenocarcinoma, and large cell carcinoma. "Both cisplatin and carboplatin treatments in A549 and H1299, two human non-small cell lung cancer cell lines, led to the obvious accumulation of UBE2F in a dose-dependent manner, but not other neddylation components (e.g., E1: NAE1 and UBA3; E2: UBE2M; E3: RBX1 and RBX2)." (PMID 33184273, 2020).
rectum adenocarcinoma (1 paper, 2026). An adenocarcinoma arising from the rectum. "TCGA data showed that rectum adenocarcinoma patients with low UBA3 mRNA had poorer prognoses, and 27.16% of tumors expressed low UBA3 mRNA." (PMID 42055937, 2026).
Rotavirus infection (1 paper, 2025). Infection with any of the rotaviruses. "From the rotavirus infection perspective, we identified by immunoprecipitation that the viral protein VP3 competes with PFDN for binding to UBA3." (PMID 40883306, 2025).
cancer (13 papers, 2014 to 2026). A tumor composed of atypical neoplastic, often pleomorphic cells that invade other tissues. "UBA3 has been implicated in various biological processes and diseases, such as adipogenesis, oxidative phosphorylation, glucose metabolism, and cancer." (PMID 38298057, 2024). "Recently, we and another group have reported the identification of additional MLN4924-induced mutations in the UBA3 gene in several cancer cell lines." (PMID 24691136, 2014). "Furthermore, DepMap analyses showed that FP-RMS cell lines are among the most sensitive to both NAE1 and UBA3 CRISPR-mediated knockout as well as to NAE pharmacological inhibition with MLN4924 compared to other cancer cell lines." (PMID 41184241, 2025). "Furthermore, 50 signaling pathways were analyzed, among which TOM1 and UBA3 were more important for cancer proliferation, invasion and metastasis." (PMID 38298057, 2024). "UBA3 has also emerged as a potential drug target for cancer therapy." (PMID 38298057, 2024). "Indeed, overactivation of CRLs has been characterized in tumor growth and progression and the enzymes implicated in the neddylation pathway (e.g., NAE1/UBA3, UBE2M/UBE2F, NEDD8 E3 ligases) are often overexpressed in different human cancers, including MM." (PMID 37460534, 2023). "In conclusion, these results in this work support a mechanism in which high concentrations of glucose activate a neddylation pathway via downregulation of UBA3 promoter methylation, and this mechanism may be closely correlate with the overactivation of the neddylation pathway in cancers." (PMID 33996822, 2021). "Moreover, FP-RMS cell lines were among the most sensitive cancer cell lines to both NAE1 and UBA3 genetic depletion as well as NAE pharmacological inhibition with MLN4924 compared to the other cell lines." (PMID 41184241, 2025). "UBA3, UBE2M and RBX1 are important for the proliferation and apoptosis of cancer cells." (PMID 35880551, 2022).
tumor (10 papers, 2014 to 2026). "Aberrantly high expression of UBA3 has been implicated in a wide range of human malignancies and is usually associated with tumor progression through modulation of the properties of tumor cells." (PMID 37656220, 2023). "However, tumor cells are prone to forming UBA3 mutations, leading to MLN4924 resistance." (PMID 39138151, 2024). "Tumor tissues in several types of malignancies showed up-regulated levels of expression of UBA3 compared to adjacent normal controls." (PMID 37656220, 2023). "Our findings provide new insights into the role of UBA3 in establishing an immunosuppressive tumor microenvironment by modulating nuclear factor kappa B (NF-кB) signaling and the neddylation pathway." (PMID 37656220, 2023). "First, the correlations between UBA3 and immune suppressive infiltrates need further verification through in vitro experiments or tumor‐bearing animal models." (PMID 37656220, 2023). "The expression of UBA3 was found to be upregulated in tumor tissues relative to adjacent normal tissues." (PMID 33996822, 2021). "Here, we report that the NAE1 and UBA3 genes encoding the two subunits of the NEDD8-activating enzyme (NAE) heterodimer are upregulated in FP-RMS patients compared to healthy skeletal muscle tissues and highly expressed in RMS among several tumor types." (PMID 41184241, 2025). "Moreover, the overexpression of UBA3 in LUAD cells was associated with the secretion of these cytokines, and the recruitment and infiltration of immunosuppressive cells including tumor-associated macrophages (TAMs), plasmacytoid dendritic cells (pDCs), Th2 cells and T-regulatory cells (Tregs)." (PMID 37656220, 2023). "In this study, we show that both NAE1 and UBA3 are overexpressed in FP-RMS patients compared to healthy muscle tissues and several other tumor types." (PMID 41184241, 2025). "We found that UBA3 was overexpressed in ICC tissues compared to normal liver tissues and that its expression was positively correlated with tumor size, stage, and grade." (PMID 38298057, 2024). "Targeting the overactivated neddylation pathway has been demonstrated as a promising anti-tumor strategy, supported by the development of MLN4924, a potent inhibitor of the neddylation E1 subunit UBA3." (PMID 36690633, 2023).
infection (4 papers, 2018 to 2023). The state of being infected such as from the introduction of a foreign agent such as serum, vaccine, antigenic substance or organism. "Selective Uba3 knockout in T cells remarkably increases the susceptibility of mice to P. yoelii 17XNL infection." (PMID 38434245, 2023). "Concurrently, Bcl-6 protein level was remarkably lower in Uba3-deficient CD4+ T cells than in Uba3-sufficient counterparts at day 7 of infection, and the proportion of IL-21-producing CD4+ T cells in the spleen was also found to be lower in Uba3ΔT mice at this time." (PMID 30462731, 2018). "In another study involving the infection of SeV or influenza A H1N1 virus, the deficiency of UBA3 or NEDD8 in myeloid cells impaired IFN-α production and render mice more susceptible to RNA virus infection." (PMID 38434245, 2023). "Owing to the pivotal role for Uba3 in initiating the neddylation process, it is reasonable to speculate that neddylation in T cells may contribute to the resolution of infection." (PMID 30462731, 2018). "However, the upregulation of Ifnb1 was not suppressed upon UBA3 deficiency although it was slightly reduced at 4 h post-infection upon MLN4924 pretreatment." (PMID 34506605, 2021). "In our initial studies, we identified that AAV2 infection of HeLa cells upregulates crucial mediators of (APPBP1, UBA3, UBC12) of Neddylation signaling pathway." (PMID 31642343, 2019). "Genetic deletion of Uba3 in T cells resulted in a slight reduction of CD4+ T cells in the spleen, and more notably, the difference was exaggerated after P. yoelii 17XNL infection." (PMID 30462731, 2018). "In parallel with the observations in vitro, T cells expressed dramatically increased amounts of Uba3 and NEDD8-conjugated proteins within 5 days of the infection, confirming activation of neddylation in parasite-responsive T cells." (PMID 30462731, 2018). "Our data show that Neddylation genes such as APPBP1 (2.78-fold), UBA3 (5.49-fold), UBC12 (2.31-fold) and SUMOylation genes such as SAE1 (4.69-fold), SAE2 (3.12-fold), UBC9 (2.22-fold), SUMO1 (6.36-fold) were significantly upregulated as early as the 2-h time point after infection." (PMID 31642343, 2019).
UBA3 also shares sentences with these, for which no sentence is quoted: colorectal cancer (2 papers); cholangiocarcinoma (1); endometrial cancer (1); esophageal squamous cell carcinoma (1); head and neck tumor (1); Hepatic steatosis (1); hepatocellular carcinoma (1); liver cancer (1); lung squamous cell carcinoma (1); parasitemia (1); prostate carcinoma (1); renal cell carcinoma (1); thyroid carcinoma (1); viral infections (1).